NLRP1 (NLR family pyrin domain containing 1)
Diseases named in the same sentence as NLRP1 in open-access papers (continued):
Sharing a sentence is not in itself a finding about the gene and the disease.
colitis (continued). "Secoisolariciresinol diglucoside (SDG), a plant lignan isolated from flaxseed, suppresses colitis by inhibiting the activation of NLRP1 inflammasome." (PMID 34590363, 2021). "In order to determine the role of NLRP1 in acute colitis we administered Nlrp1−/− mice with 3% (w/v) DSS ad libitum in their drinking water for 6 days." (PMID 30214011, 2018). "While single-housed WT mice displayed severe DSS-induced colitis as expected, WT mice that were co-housed with Nlrp1−/− mice and the single-house Nlrp1−/− mice showed reduced signs of colitis." (PMID 30214011, 2018). "Here we show that the inflammasome sensor Nlrp1 aggravates DSS-induced experimental mouse colitis by limiting beneficial, butyrate-producing Clostridiales in the gut." (PMID 30214011, 2018). "Further, NLRP1 activated IL-18 contributes to DSS-induced colitis phenotype." (PMID 38455052, 2024). "However, another report’s results indicate that NLRP1 lacks the ability to inhibit DSS-induced colitis by promoting beneficial, butyrate producing Clostridium expansion." (PMID 38455052, 2024). "NLRP1 plays a role in regulating microbiome composition and has protective effects on colitis, while its absence gives rise to the proliferation of pathogenic bacteria that induce dysbiosis and consequently exacerbate intestinal inflammation and impair the function of the intestinal barrier." (PMID 39684769, 2024). "Thus, we searched the literature and found that several compounds affect the development of colitis by targeting NLRP1 and NLRP6." (PMID 36090968, 2022). "Instead, IL‐18 activation by NLRP1 contributes to DSS‐induced colitis phenotype." (PMID 34705319, 2021). "Here the authors show that, in mouse experimental colitis models, Nlrp1 inflammasome sensor activates IL-18 to reduce beneficial colonic Clostridiales species, thereby decreasing microbial butyrate and its protective effects on colitis." (PMID 30214011, 2018). "As expected, depleting the elevated bacteria from Nlrp1-deficient mice meant that they no longer had a protected DSS-colitis phenotype compared to WT mice." (PMID 30214011, 2018). "We have shown that IL-18 is involved in the exacerbation of DSS-colitis after activation of NLRP1." (PMID 30214011, 2018). "In order to identify whether NLRP1 activity in the non-hematopoietic or hematopoietic compartment was detrimental during DSS-induced colitis, we generated reciprocal bone marrow chimeras, whereby WT and Nlrp1−/− mice were lethally irradiated and reconstituted with either WT or Nlrp1−/− bone marrow." (PMID 30214011, 2018). "Secoisolariciresinol diglucoside (SDG), an inhibitor of the NLRP1 inflammasome, disrupts downstream NF-κB activation, which also ameliorated DSS-induced colitis." (PMID 37833958, 2023). "Regulation of the NLRP3 inflammasome using herbal compounds can affect the development of colitis via multiple mechanisms, whereas previous studies have shown that other inflammasome forming NLRs such as NLRP1, NLRP6, NLRC4 and AIM2 are also involved in the pathogenesis of colonic inflammation." (PMID 36090968, 2022). "This also agrees with our observation that deletion of NLRP1 from non-hematopoietic cells conferred protection against DSS-induced colitis." (PMID 30214011, 2018). "This indicates that Nlrp1 activation contributes to DSS-induced colitis, with decreased butyrate production, even in the absence of IL-1 signaling." (PMID 30214011, 2018). "Although genetic deletion of IL-1R did not rule out a contribution from IL-1β downstream of Nlrp1 in DSS-colitis, it did implicate IL-18 in this process." (PMID 30214011, 2018). "Therefore, NLRP1 may be a potential therapeutic target for IBD, and its contribution to colitis may relate to gut microbiota composition." (PMID 38455052, 2024).
diabetes (14 papers, 2013 to 2026). "Here, we assessed the effect of the common NLRP1 variant M1184V, associated with asthma, inflammatory bowel disease, and diabetes, on the protein level." (PMID 36309085, 2022). "Notably, NLRP1 deficiency has been shown to mitigate retinal abnormalities induced by diabetes in a streptozotocin-induced diabetic mouse model." (PMID 38336763, 2024). "Supporting these findings, diabetes‐associated metabolites (high glucose and glycated albumin) were used to mimic the diabetic milieu in monocytes from healthy individuals and were found to increase NLRP1 expression." (PMID 33682108, 2021). "A recent study has also suggested that the formation and activation of the NOD-like receptor protein 1 (NLRP1) inflammasome induces neuroinflammation and neuron injury during hyperglycemia, thus representing a novel mechanism of diabetes-associated neuron injury." (PMID 28900628, 2017). "Therefore, NLRP1 inflammasome may play a different role on diabetes under different status and tissues, and the cause of inflammatory cytokines may be affected by other inflammasomes interfering factor." (PMID 36993972, 2023). "In conclusion, we identify significant associations between 4 SNPs (NLRP1 rs12150220, IL2RA rs11594656, CLEC16A rs725613 and APOA5 −1131T/C) and diabetes." (PMID 23922971, 2013). "Genetic polymorphisms in NLRP3, NLRP1, or IL−1β genes influence individual inflammatory responses, and not all patients—especially in diabetes—display inflammasome-driven pathology." (PMID 41488670, 2025). "NLRP1, age, diabetes, TG, LDL-C, FIB, and NE were used for multivariate binary logistic analysis." (PMID 37214347, 2023). "Interestingly, NLRP1 has been shown to have a protective role in diabetes." (PMID 33682108, 2021). "The results showed that the levels of NLRP3 in the kidneys of the diabetes group were higher than those in the normal group (P < 0.05), but the level of NLRP1 did not change significantly compared with that of the normal group (P > 0.05)." (PMID 35399795, 2022). "Age, smoking, diabetes mellitus (DM), hyperlipidemia,the serum level of nucleotide-binding oligomerization domain (NOD)-like receptorprotein 1 (NLRP1), alkaline phosphatase (ALP) and triglycerides (TG) wereidentified as independent risk factors of CAC." (PMID 39139411, 2024). "However, HIIT appeared to attenuate the negative effects of diabetes on cardiac function, histopathology, NLRP1, ATP-releasing channels, inflammation and apoptosis." (PMID 38532054, 2024). "However, as the disease progressed, NLRP1 and NLRP3 inflammasomes failed to exert their protective effects during diabetic ketoacidosis and showed significant decline." (PMID 36993972, 2023).
Sepsis (14 papers, 2018 to 2025). Sepsis is defined as life-threatening organ dysfunction caused by a dysregulated host response to infection. "Specific inhibition of caspase-1 reduces NLRP1 inflammasome expression, and suppresses sepsis, inflammatory cytokine secretion and leukocyte aggregation in septic shock mouse models." (PMID 40153575, 2025). "The study identified seven important PRGs including CHMP7, NLRC4, PLCG1, IRF1, CASP4, NLRP1, GSDMD associated with sepsis." (PMID 37939116, 2023). "According to the ROC curves, four out of six genes (GZMB, CHMP7, NLRP1, and AIM2) had good diagnostic value in the diagnosis of sepsis, with AUC > 0.9 in both the GSE65682 and GSE95233 datasets." (PMID 36618365, 2022). "Four out of six genes (GZMB, CHMP7, NLRP1, and AIM2) also have potential diagnostic value in sepsis diagnosis." (PMID 36618365, 2022). "Artificial intelligence systems identified eight out of twenty novel genetic markers (SDC4, CLEC5A, TCN1, MS4A3, HCAR3, OLAH, PLCB1, and NLRP1) that help predict sepsis severity or mortality." (PMID 33692779, 2021). "Attenuation of sepsis-induced acute kidney injury was due to the prohibited production of inflammatory cytokines and decrease expression of Caspas-1, NLRP-1, IL-1β, and IL-18 in renal tissues." (PMID 34222479, 2021). "To explore whether AC-YVAD-CMK could affect the NLRP1 inflammasome signaling pathway to improve sepsis-induced acute kidney injury, we measured the expression levels of Caspas-1, NLRP-1, IL-1β, and IL-18 by Western blotting." (PMID 34222479, 2021). "In both datasets, the expression level of AIM2, ELANE, and MYD88 were significantly higher in sepsis patients compared to healthy individuals, while the expression level of CHMP7, GZMB, and NLRP1 were significantly lower." (PMID 36618365, 2022). "Then, we developed a prognostic risk score with six pyroptosis-related genes, including GZMB, CHMP7, NLRP1, MYD88, ELANE, and AIM2, and found that it could predict the prognosis of sepsis patients." (PMID 36618365, 2022). "Previous publications have found a significantly lower expression of NLRP1 and a significantly higher expression of AIM2 among sepsis patients, besides, an even lower expression of NLRP1 was found in the non-survivor." (PMID 36618365, 2022). "The results showed that AC-YVAD-CMK treatment significantly reduced the expression levels of Caspas-1, NLRP-1, IL-1β, and IL-18 compared with those of the CLP group, confirming that AC-YVAD-CMK could reduce pyroptosis and sepsis-induced acute kidney injury." (PMID 34222479, 2021). "The results obtained in other kinds of cytosolic PRRs (e.g., NLRP1, AIM2, or NLRC4) were not representative of the entire pathophysiology encountered in sepsis." (PMID 33679687, 2020).
Stroke (14 papers, 2015 to 2023). Sudden impairment of blood flow to a part of the brain due to occlusion or rupture of an artery to the brain. "In stroke patients, the expression of NLRP1 will increase and will activate the inflammatory reaction and eventually lead to neuronal death." (PMID 37214347, 2023). "NLRP1 is predominantly expressed in neuronal cells after stroke and, owing to its unique pyrin structural domain, can bind directly to procaspase-1, thereby facilitating Caspase-1 cleavage of GSDMD with the pro-inflammatory factor IL-1." (PMID 37165005, 2023). "A study investigated the increased expression of NLRP1 immediately following stroke which was maintained at 12, 24, and 72-h." (PMID 37822799, 2023). "The chemokine receptors CCR5 and CXCR4 on neuronal cells have all been shown to be involved in the assembly of NLRP1 after stroke." (PMID 37165005, 2023). "The work focused on NLRP3 is the most systematic study, followed by NLRP1, NLRP2, and NLRC4 among the inflammasomes associated with stroke." (PMID 34233704, 2021). "The evidence for the role of NLRP1/3 inflammasomes and pyroptosis in stroke pathology was well defined in the previous studies." (PMID 34646128, 2021). "We found that NLR family pyrin domain containing 3 (NLRP3) was the most studied, followed by NLRP1, NLRP2, and NLRC4 among the inflammasomes associated with stroke." (PMID 34233704, 2021). "NLRP1 inflammasome complex is up-regulated in rat cortical neurons after traumatic brain injury, stroke and hippocampal aging." (PMID 34106880, 2021). "Comparable results showed an elevated expression of NLRP3 inflammasome components and downstream effector targets in conjunction with NLRP1 in mouse and human brain tissue compromised by stroke." (PMID 32635451, 2020). "Expression levels of NLRP3 and NLRP1, as well as cleavage products of caspase‐1, IL‐1β, and IL‐18, were shown to be elevated in postmortem brain tissue of stroke patients." (PMID 31015277, 2019). "Interestingly, NLRP3 immunoreactivity dominantly increased in our stroke model compared to the NLRP1 inflammasome." (PMID 37822799, 2023). "Apart from neuronal expression, NLRP1 inflammasome has also been found in astrocytes and microglia/macrophages with a complex spatial and temporal expression pattern in the mouse brain after stroke." (PMID 32635451, 2020). "The NLRP1 inflammasome was the first inflammasome identified to form and be activated post-stroke." (PMID 26690125, 2015). "The sudden cessation of blood in stroke leads to a decrease in ATP that activates AMP-activated protein kinase (AMPK) and subsequently the activation of NLRP1." (PMID 34112082, 2021). "Pharmacological targeting of either the NLRP1 or NLRP3 inflammasomes has been shown to reduce innate immune responses and reduce infarct size post-stroke." (PMID 26690125, 2015). "Neuroinflammation, especially that driven by NLRP1, plays a considerable role in the pathophysiology of brain injury, such as early brain injury (EBI) of subarachnoid hemorrhage, ischemic brain injury during stroke, and traumatic brain injury (TBI)." (PMID 35707533, 2022). "It was shown that in early stroke NLRP1, NLRC4 or AIM2 did not have significant effects, while NLRP3 was predominantly expressed in ischemic neurons, and its inhibition improved neurologic outcome with a reduction in infarct size." (PMID 34112082, 2021). "Accordingly, NLRP1 and AIM2 were present in the clots of nine patients with stroke." (PMID 33569001, 2020). "Finally, an expression analysis in the peri‐infarct zone of transient MCAO rats revealed elevated levels of the inflammasome components NLRP1, NLRP3, AIM2, NLRC4, and ASC, consistent with the potential activation of multiple inflammasomes in stroke." (PMID 31015277, 2019).
Stroke (continued). "To determine which NLR sensor molecules were present in the clot of patients with stroke, we immunoblotted samples for NOD-like receptor protein-1 (NLRP1) and Absent in Melanoma-2 (AIM2); two receptors that form protein-protein interactions with caspase-1 and ASC to form an inflammasome complex." (PMID 33569001, 2020).
viral infection (14 papers, 2021 to 2026). "The discovery that mouse NLRP1B shares features with human NLRP1 could allow the development of animal models to study the role of the tripwire in antiviral defenses and the overactive inflammation associated with some viral infections." (PMID 33410748, 2021). "In immortalized and primary human keratinocytes, we find that NLRP1 inflammasome activation by dsRNA, including during viral infection, requires the MAPK kinase kinase TAK1." (PMID 41648573, 2026). "Collectively, we reveal TAK1 as a novel activator of the NLRP1 inflammasome, functioning as a critical signaling hub linking NLRP1 to inflammatory responses in the context of viral infection and autoimmunity." (PMID 41648573, 2026). "NLRP1 is activated by viral 3 C proteases, double stranded RNA generated upon viral infection, and by inhibition of binding to dipeptidyl peptidase 8/9 or to oxidized thioredoxin, which restrain NLRP1 activation." (PMID 40593496, 2025). "Taken together, these results suggest that the NLRP1 inflammasome triggers innate immunity to clear viral infection and inhibit viral persistence." (PMID 37515138, 2023). "As NLRP1 inflammasome activation by alphavirus infection depends on p38 kinase activity and neddylation, virus infection likely activates NLRP1 by a mechanism that resembles activation by the ribotoxic stress response." (PMID 36315050, 2023). "Further in vivo studies will help determine the role of NLRP1 in antiviral immunity and/or immunopathology during viral infection." (PMID 33410748, 2021). "Further experiments confirmed that when a picornavirus enzyme cuts through this region during a viral infection, it triggers NLRP1 to activate the inflammasome and initiate an immune response." (PMID 33410748, 2021). "To further confirm that 3Cpro cleavage (or lack thereof) of NLRP1 is reflective of 3Cpro during viral infection, we infected cells expressing WT or 131P NLRP1 with EMCV." (PMID 33410748, 2021). "In NLRP1 deficient cells, virus infection fails to induce caspase-8/-3 activation and subsequent GSDME cleavage." (PMID 38932190, 2024). "However, recent studies have found that activation of human NLRP1 by both ZAKα/P38 axis following ribotoxic stress response and viral infection and by the ORF45 protein of the Kaposi's sarcoma‐associated herpesvirus are independent of DPP9." (PMID 37675820, 2023). "To study NLRP1 activation in response to viral infection, we thus infected HEKNLRP1+ASC, HEKNLRP3+ASC, and N/TERT-1C1C-EGFP cells with SFV, the closely related Sindbis virus (SINV), as well as vesicular stomatitis virus (VSV), a negative-sense single-stranded RNA virus." (PMID 36315050, 2023). "Understanding the types of viruses that activate the NLRP1 inflammasome, and the outcomes of the resulting immune response, may have implications for future treatments of viral infections." (PMID 33410748, 2021). "Furthermore, long dsRNA, originating from viral infections, activates NLRP1 through direct binding." (PMID 38920661, 2024). "Interestingly, NLRP1 senses viral infection also through a second mechanism." (PMID 38920661, 2024). "This comprehensive review synthesizes the diversified landscape of inflammasome activation during viral infections, extending beyond the canonical NLRP3 inflammasome to include specialized sensors such as NLRP6, NLRP9, NLRP1, NLRP12, and NLRC4." (PMID 42198749, 2026). "However, upon recognition of viral infection, the ORF45 structural protein of KSHV binds to Linker1, inhibiting NLRP1 activation and inflammasome assembly." (PMID 37608944, 2023). "However, it is not clear how the inflammasome is activated following a viral infection and NLRP1 activation." (PMID 37723427, 2023). "However, increased production of the C-terminal fragment of NLRP1, such as during viral infection, is thought to decrease intact NLRP1, rendering this DPP9 checkpoint dysfunctional, resulting in the release of the C-terminal fragment, which in turn leads to NLRP1 activation." (PMID 36189327, 2022).